PTK6 (protein tyrosine kinase 6)
Diseases named in the same sentence as PTK6 in open-access papers (continued):
Sharing a sentence is not in itself a finding about the gene and the disease.
breast carcinoma (continued). "PTK6 overexpression was sufficient to enhance growth of ER+ breast cancer cells in full growth medium culture conditions, as well as in the presence of tamoxifen and estrogen-deprived cultures conditions (e.g., charcoal-stripped serum, phenol red-free medium)." (PMID 29167821, 2017). "In this study, we investigated the functions of PTK6 in ER+ Luminal breast cancer cells, including those that are relatively resistant to estrogen deprivation or targeted endocrine therapies used in the treatment of ER+ cancers." (PMID 29167821, 2017). "We sought to determine the mechanisms responsible for apoptosis induced by PTK6 downregulation in ER+ breast cancer cells." (PMID 29167821, 2017). "Downregulation of PTK6 in ER+ breast cancer cells, including those resistant to tamoxifen, fulvestrant, and estrogen deprivation, induces apoptosis, as evidenced by increased levels of cleaved PARP, and an increase in the AnnexinV+ population." (PMID 29167821, 2017). "Down-regulation of PTK6 induced apoptosis in lapatinib-resistant, Her2-positive breast cancer cells by enhancing Bim expression." (PMID 27311570, 2016). "PTK6 is overexpressed in many epithelial tumors, including breast cancer, non-small cell lung cancer, and ovarian cancer, and is associated with poor patient survival." (PMID 27311570, 2016). "PTK6 downregulation induces apoptosis of Lapatinib-resistant Her2+ breast cancer cells by enhancing Bim expression via p38 activation." (PMID 26084280, 2015). "Several studies with human tumor cell lines have suggested PTK6 contributes to ERBB2-induced breast cancer." (PMID 26247733, 2015). "Among the molecular subtypes of breast cancer, estrogen receptor (ER)+ and Her2+ cancers express the highest levels of PTK6 transcript." (PMID 26084280, 2015). "Our studies also show for the first time a link between p38 signaling and PTK6-dependent Bim regulation in Her2+ breast cancer cells." (PMID 26084280, 2015). "Small molecule inhibitors of PTK6 should prove useful in determining the role of PTK6 kinase activity in Bim and apoptosis regulation of Her2+ breast cancer cells." (PMID 26084280, 2015). "• Lapatinib treatment of sensitive, but not resistant, HER2+ breast cancer cells led to increased Bim expression.• Downregulation of PTK6 induced apoptosis of resistant breast cancer cells through a Bim-dependent mechanism." (PMID 26405162, 2015). "We initially identified protein tyrosine kinase 6 (PTK6) as a critical mediator of anoikis resistance of breast cancer cells in a functional genomic screen designed to identify regulators of anchorage-independent survival." (PMID 26084280, 2015). "Our data support the clinical translation of PTK6 inhibition as a therapeutic strategy for Her2+ breast cancers, including those resistant to currently available targeted therapies." (PMID 26084280, 2015). "In this study, we sought to determine the effects of PTK6 inhibition on growth and survival of Lapatinib-resistant Her2+ breast cancer cells." (PMID 26084280, 2015). "We previously reported that PTK6 transcript is highly expressed in the Her2+ subtype and downregulation enhances anoikis of Her2+ breast cancer cells." (PMID 26084280, 2015). "Overexpression of PTK6 enhances anchorage-independent survival, proliferation, and migration of breast cancer cells." (PMID 26084280, 2015). "We sought to determine the mechanisms by which PTK6 regulates survival of Lapatinib- resistant Her2+ breast cancer cells." (PMID 26084280, 2015). "To determine the effects of PTK6 inhibition on Lapatinib-resistant Her2+ breast cancer cell lines (UACC893R1 and MDA-MB-453), we used short hairpin ribonucleic acid (shRNA) vectors to downregulate PTK6 expression." (PMID 26084280, 2015). "Our studies show for the first time a link between PTK6, pro-apoptotic Bim and apoptosis of Her2+ breast cancer cells." (PMID 26084280, 2015).
breast carcinoma (continued). "Castro and Lange reported that in breast cancer cells the PTK6/ERK5 complex is critical for growth factor induced cell migration, while PTK6 still increases cellular migration by ERK1/2 activation in keratinocytes when ERK5 is knocked down." (PMID 24788754, 2014). "Recently, PTK6 was shown to be regulated by hypoxia-inducible factors 1α/2α and proposed to be a mediator of hypoxia-induced breast cancer progression." (PMID 25153721, 2014). "Significant levels of PTK6 expression are detected in most human breast tumors and breast cancer cell lines." (PMID 25153721, 2014). "Similar to findings in human breast cancer, we recently demonstrated that PTK6 is induced in mouse mammary gland tumors of different origins, including spontaneous tumors and ERBB2 (HER2) induced tumors." (PMID 25153721, 2014). "PTK6 is expressed in breast cancer cell lines representing different molecular subtypes of breast cancer." (PMID 25153721, 2014). "For example, PTK6 has been extensively studied in breast cancers for its pro-oncogenic roles including cell cycle progression, angiogenesis, anoikis resistance and cellular migration, while PTK6 has been shown to work anti-oncogenically in esophageal cancer." (PMID 24788754, 2014). "Irie and colleagues also found increased PTK6 expression in all breast cancer subtypes except basal when they analyzed three different data sets (Van't Veer, Hu, and Lu)." (PMID 25153721, 2014). "The most intense cytoplasmic PTK6 staining was detected in invasive ductal carcinomas, while the highest nuclear PTK6 signals were detected in lobular carcinoma in situ." (PMID 25153721, 2014). "PTK6 was identified in human metastatic breast cancer, and is overexpressed in the majority of human breast cancers and in most breast tumor cell lines." (PMID 25153721, 2014). "Cumulatively, these results suggest that PTK6 expression levels can serve as a tool for predicting breast cancer survival when the status of PTK6 protein activation is unavailable." (PMID 25153721, 2014). "Over-expression of PTK6 was shown to increase proliferation, anchorage-independent growth, cell migration, and tumor growth in many kinds of breast cancer model system, while knocking-down of PTK6 leaded to the opposite results." (PMID 23758975, 2013). "For instance, the elevated expression of PTK6 was detected in breast cancer cell lines and more than 65% primary breast cancers, but was undetectable or at a low level in normal mammary tissue and benign lesions." (PMID 23758975, 2013). "Interesting, according to several in vitro studies using both knockdown and overexpression systems, PTK6 was shown to increase proliferation, anchorage-independent growth, cell migration, and tumor growth in breast cancer models." (PMID 23758975, 2013). "In fact, p38, ERK5, and MEF2C itself have been recently described as novel downstream Brk (PTK6) effector pathways supposedly playing a role in primary breast cancer." (PMID 22952604, 2012). "PTK6 was first discovered in a screen for tyrosine kinases expressed in human cultured melanocytes, and it was later cloned from human breast cancer cells and the gastrointestinal tract of the mouse." (PMID 21479203, 2011). "The RNA and protein expression of both full-length PTK6 and ALT-PTK6 was previously reported in the T47D human breast cancer cell line." (PMID 21479203, 2011). "An alternatively spliced PTK6 transcript that encodes a 15 kDa protein including the PTK6 SH3 domain and a unique proline-rich carboxy-terminus was previously detected in the T47D human breast cancer cell line." (PMID 21479203, 2011). "In two large breast cancer patient cohorts with long-term follow up, tumor specimens were stratified based on PTK6 expression levels." (PMID 20668531, 2010). "In breast cancer tissue significant correlation was identified between the expression levels of PTK6 and HER2." (PMID 20700126, 2010).
breast carcinoma (continued). "PTK6 is highly expressed not only in the previously reported Her2+ breast cancer subtype, but also in high grade ER+, Luminal B tumors and high expression is associated with adverse outcomes." (PMID 20668531, 2010). "Here we demonstrate a critical role for PTK6 in anchorage-independent survival of specific subtypes of breast cancer cells." (PMID 20668531, 2010). "In our study we analyzed the prognostic significance of elevated PTK6 transcript expression in multiple large cohorts of patients with breast cancer." (PMID 20668531, 2010). "Protein tyrosine kinase 6 forms protein complexes with HER2 in primary breast cancer tissues, which can be visualised by use of the PLA technique." (PMID 20700126, 2010). "Examination of a panel of cell lines revealed that PTK6 was abundantly expressed in several Her2+ breast cancer lines, as previously reported." (PMID 20668531, 2010). "This death was inhibited by the caspase inhibitor ZVAD-fmk, again supporting a role for PTK6 in modulating apoptosis of breast cancer cells under matrix-detached conditions." (PMID 20668531, 2010). "In another study, however, PTK6 staining intensities were found to correlate with the histological grade of 250 breast carcinomas." (PMID 18781181, 2008). "PTK6 was shown to be overexpressed in two-thirds of breast carcinomas, and expression is elevated in colon tumours and several cancer cell lines." (PMID 18781181, 2008). "We show that PTK6 expression is of significant prognostic value in the outcome of breast carcinomas." (PMID 18781181, 2008). "Knockdown of PTK6 decreases proliferation in breast cancer cell lines and blocks activity of a GTPase, of ERK5 (extracellular signal-regulated kinase) and p38 mitogen-activated protein kinase (MAPK), but not Akt." (PMID 18781181, 2008). "As recently reported by us, PTK6 protein expression has prognostic value in a small set of 105 breast carcinomas, and correlates with the expression of HER receptors." (PMID 18781181, 2008). "In this study, we investigated protein expression of the cytoplasmic protein kinase PTK6 (BRK), the HER receptors, Sam68, PTEN, MAPK, and P-MAPK in breast carcinomas, and tested the associations between these markers and patient prognosis." (PMID 18781181, 2008). "We performed a retrospective study on archival breast cancer samples from patients with long follow-up and compared the protein expression between individual HERs and between HERs and the PTK6." (PMID 17299391, 2007). "In normal breast epithelium, PTK6 is low or undetectable, but the protein is overexpressed in many breast carcinomas, suggesting, PTK6 expression is related to carcinogenesis." (PMID 17299391, 2007). "PTK6 can promote tumorigenesis of breast cancer, lung cancer, colorectal cancer, and other tumors." (PMID 36690663, 2023). "PTK6 can promote the tumorigenesis of breast cancer by interacting with the EGFR pathway." (PMID 36690663, 2023). "Clinically, the interaction between PTK6 and EGFR has wide implications, as PTK6 may potentially be a factor in the low efficacy of anti-EGFR drugs in breast cancer treatment." (PMID 37509364, 2023). "Other studies have also shown that Hsp90 plays an important role in regulating the stability of PTK6, raising the possibility that Hsp90 inhibitors may be used as therapeutic drugs for PTK6-positive cancers,including breast cancer." (PMID 37932734, 2023). "More experiments may be needed in the future to uncover this phenomenon.PTK6 expression has been studied in different breast cancer subtypes." (PMID 37932734, 2023). "Furthermore, PTK6 inhibits the apoptosis of lapatinib-resistant Her2-positive breast cancer cells by suppressing Bim expression through p38 inactivation." (PMID 35562900, 2022). "PTK6 has been most well studied in breast cancer, prostate cancer, and multiple cancer." (PMID 36158685, 2022). "However, PTK6 is overexpressed in breast cancer and prostate cancer, and it is activated at the plasma membrane in these tumors." (PMID 36228719, 2022).
breast carcinoma (continued). "We silenced PTK6 gene expression with two different well-validated shRNAs in the PC-3 and C4-2B prostate cancer cell lines, the lung cancer cell line PC-9, and the breast cancer cell line T47-D." (PMID 36228719, 2022). "PTK6 promoted the proliferation, survival, and metastasis of breast cancer." (PMID 34551797, 2021). "PTK6 inhibition also overcomes targeted therapy resistance of HER2+ breast cancer." (PMID 29167821, 2017). "Given the recent development of multiple PTK6 small molecule inhibitors, our ongoing studies will assess the efficacy of PTK6 inhibitor treatment, alone or in combination with endocrine therapy, with respect to suppression of ER+ breast cancer cell growth." (PMID 29167821, 2017). "PTK6 expression has prognostic significance for patients with ER+ breast cancers." (PMID 29167821, 2017). "Here, we report on the role of protein tyrosine kinase 6 (PTK6) in survival and growth of ER+ Luminal breast cancer cells, including those resistant to standard endocrine therapies used in the treatment of patients with ER+ breast cancers." (PMID 29167821, 2017). "PTK6 is critical not only for the growth of ER+ breast cancer cells that are resistant to tamoxifen, but also for the growth of ER+ breast cancer cells made resistant to long-term estrogen deprivation (MCF-7-EDR; T47D-EDR) or to the selective ER degrader fulvestrant (MCF-7-FulvR)." (PMID 29167821, 2017). "Our results suggest that PTK6 may be an attractive candidate therapeutic target to inhibit growth of ER+ breast cancer cells, including endocrine therapy-resistant cells." (PMID 29167821, 2017). "Further, PTK6 has been indicated as a prognostic factor for long-term breast cancer survival." (PMID 28650989, 2017). "In this study, we report for the first time that inhibition of PTK6 induces apoptotic cell death of Her2+ breast cancer cells that are relatively resistant to Lapatinib at baseline or after continuous treatment in the presence of this Her2 tyrosine kinase inhibitor (TKI)." (PMID 26084280, 2015). "As Bim expression is a critical biomarker for response to many targeted therapies, PTK6 inhibition may offer a therapeutic approach to treating patients with Her2 targeted therapy-resistant breast cancers." (PMID 26084280, 2015). "Including PTK6 inhibitors as part of a treatment regimen could have distinct benefits in ERBB2/HER2-positive breast cancers." (PMID 26247733, 2015). "Several studies have suggested that PTK6 is a potential therapeutic target in breast cancer." (PMID 25153721, 2014). "However, over-expression of PTK6 is a common phenomenon in a variety of epithelial tumors, such as breast cancer, ovarian cancer, colon cancer, head and neck cancer, non-small cell lung cancer (NSCLC), and metastatic melanoma." (PMID 23758975, 2013). "Several studies indicate that PTK6 promotes oncogenic signaling in breast cancer cells." (PMID 21479203, 2011). "Inhibition or downregulation of PTK6 may also prove to be an effective strategy for enhancing the response of high-grade ER+/Luminal B breast cancers to endocrine therapy or overcoming acquired resistance to these agents." (PMID 20668531, 2010). "Our findings show that HER2–PTK6 protein complexes are of prognostic value and that PTK6 may be considered as additional breast cancer biomarker and potential target for anticancer therapy." (PMID 20700126, 2010). "Our finding that elevated expression of PTK6 transcript correlates with adverse outcomes for patients with breast cancer in all cohorts analyzed is consistent with a recently reported correlation between PTK6 mRNA levels and tumor grade based on analyses of 44 tumors." (PMID 20668531, 2010). "To analyse whether significant correlations among the expression level of different protein markers in tumour tissue are based on possible complex formation between these proteins, we performed IP with the PTK6 antibody using the T47D breast cancer cell line." (PMID 18781181, 2008).
breast carcinoma (continued). "Two-thirds (69%, n=293) of the breast carcinomas showed a high PTK6 expression (IHC 2+, 3+)." (PMID 18781181, 2008). "Although several interaction partners of PTK6 have been identified in cellular cultures, the signalling function of PTK6 as well as its function in breast cancer development and prognosis remains unclear." (PMID 18781181, 2008). "In normal breast epithelium, PTK6 expression is low or undetectable, but it is elevated in many breast carcinomas, indicating that PTK6 overexpression may be related to carcinogenesis." (PMID 18781181, 2008). "On the basis of these results, we suggest that PTK6 may serve as a future target for the development of novel treatments in breast cancer." (PMID 18781181, 2008). "Besides, PTK6 also stops breast cancer cells from going into autophagy, ensuring their survival." (PMID 38573548, 2024). "However, the mechanism of this difference remains unclear and may be due to differences in tumor type, sample size, and statistical methods.PTK6 regulates RhoA and Ras via phosphorylation of p190 to promote the growth, migration and invasion of breast cancer." (PMID 37932734, 2023). "Therefore, PTK6 is an attractive candidate therapeutic target for ER+ breast cancer." (PMID 29167821, 2017). "In conclusion, our study supports PTK6 inhibition as a strategy to induce apoptosis of Lapatinib-resistant Her2+ breast tumors by enhancing expression of pro-apoptotic Bim that may be suppressed via multiple mechanisms in breast cancers." (PMID 26084280, 2015). "We hypothesized that PTK6 inhibition is an effective strategy to inhibit growth and survival of Her2+ breast cancer cells, including those that are relatively resistant to Lapatinib, a targeted therapy for Her2+ breast cancer, either intrinsically or acquired after continuous drug exposure." (PMID 26084280, 2015). "Thus, potentially, PTK6 may represent a therapeutic target in clinical management of breast cancer in addition to the established anti-HER2 therapy with the humanised antibody trastuzumab, which targets HER2, but progression is common within 1 year." (PMID 20700126, 2010). "No study has so far tested the hypothesis that PTK6 may have an impact upon breast cancer prognosis or tested its association with the HER family of RTKs in breast carcinoma tissue." (PMID 17299391, 2007). "Here we have shown that SNAIL is a novel substrate of MARCH2 E3 ligase activity in breast cancer cells, and the MARCH2–SNAIL interaction is enhanced by PTK6 inhibition." (PMID 38457262, 2024). "Both transcription factors are directly phosphorylated by PTK6 and STAT3, when activated, promotes proliferation and migration and impairs apoptosis in colon cancer cell lines, mouse models, and breast cancer cell lines MDA-MB-231 and T47D." (PMID 37509364, 2023). "MK138 and MK150, the two most potent derivatives of Tilfrinib, selectively inhibit PTK6 and suppress STAT3 activity in T47D breast cancer cell lines." (PMID 37509364, 2023). "Tilfrinib (4f) 4-anilino α-carbolines mediated PTK6 inhibition shows anti-proliferative effects on MCF7, HS-578/T, and BT-549 breast cancer cell lines." (PMID 37509364, 2023). "The suppressor of cytokine signaling 3 (SOCS3) protein has been identified as the first potent biological inhibitor of PTK6, showing a tumor suppressive effect in T47D and MDA-MB-231 breast cancer cell lines." (PMID 37509364, 2023). "PTK6 inhibitors such as XMU-MP-2 and Tilfrinib have demonstrated potency and selectivity in breast cancer cells when used in combination with chemotherapy, indicating the potential for PTK6 targeted therapy in cancer." (PMID 37509364, 2023). "PTK6 cooperates with HER2 and Src to regulate cell survival and EMT in HER2-positive breast cancer cells." (PMID 35562900, 2022). "Expression of Protein tyrosine kinase 6 (PTK6) is upregulated in several human solid tumors, and it has oncogenic roles in prostate and breast cancer." (PMID 36228719, 2022).